PDE4D (phosphodiesterase 4D)
Diseases named in the same sentence as PDE4D in open-access papers (continued):
Sharing a sentence is not in itself a finding about the gene and the disease.
Hepatic steatosis (2 papers, 2023 to 2025). Steatosis is a term used to denote lipid accumulation within hepatocytes. "Second, a high‐fat diet induces hepatic steatosis with a concomitant increase of hepatic PDE4D in mice, while over‐expression of PDE4D by adeno‐associated virus 8 in wild‐type livers directly resulted in hepatic steatosis in the absence of a high‐fat diet." (PMID 40851490, 2025). "To investigate the role of PDE4D deficiency in HFD-induced hepatic steatosis, liver tissue was stained with HE and Oil red O. As we expected, HFD-induced hepatic ballooning and lipid deposition were alleviated by liver PDE4D deletion." (PMID 37072403, 2023). "Together, these findings indicated that PDE4D deficiency in the liver improved HFD-induced hepatic steatosis and associated renal damage." (PMID 37072403, 2023). "Our study demonstrated that PDE4D overexpression in the liver induced hepatic steatosis." (PMID 37072403, 2023). "Furthermore, liver-specific knockout of PDE4D or pharmacological inhibition of PDE4 with roflumilast ameliorated hepatic steatosis and kidney injury in HFD-fed diabetic mice." (PMID 37072403, 2023). "We found that mice fed a high-fat diet (HFD) for 16 weeks developed hepatic steatosis and kidney injury, with an associated increase in hepatic PDE4D but no changes in renal PDE4D." (PMID 37072403, 2023).
Hyperinsulinemia (2 papers, 2025). An increased concentration of insulin in the blood. "Hyperinsulinemia-induced PDE4D expression via β2AR impaired adrenergic regulation in a diabetic model." (PMID 40015131, 2025).
idiopathic dilated cardiomyopathy (2 papers, 2022 to 2025). Decreased function of the heart associated with cardiac enlargement and congestive heart failure, of unknown cause. "Studies show that PDE4A and PDE4D are significantly reduced in the hearts of patients with idiopathic dilated cardiomyopathy." (PMID 39662482, 2025). "PDE4D represents the main PDE4 isoform in the human heart and its expression is decreased in idiopathic dilated cardiomyopathy as well as in rats during early angiotensin II-induced cardiac hypertrophy, although total cAMP-PDE activity was increased." (PMID 36142518, 2022).
liver cancer (2 papers, 2022). An epithelial or non-epithelial malignant neoplasm that arises from the liver. "Specificity of action remains important; for example, the recent observation that PDE4D inhibition exerts anti-oncogenic action in liver cancer would be unlikely to apply to fibrolamellar hepatocellular carcinoma." (PMID 36313756, 2022).
lung adenocarcinoma (2 papers, 2015 to 2025). A carcinoma that arises from the lung and is characterized by the presence of malignant glandular epithelial cells. "Additionally, both RBMX and PDE4D have been proposed as potential predictors of response to immunotherapy in patients with lung adenocarcinoma." (PMID 40430005, 2025). "In an exploratory analysis, the protein and mRNA expression levels of DGKa, PDE4A and PDE4D were examined in the five EGFR-mutant lung adenocarcinoma cell lines in an effort to explore whether DGKa regulates MTOR transcription through modulation of cAMP levels." (PMID 26639561, 2015).
memory impairment (2 papers, 2020 to 2021). "The present study suggested that PDE4D knockdown by microinjection of lenti-PDE4D-miRNA into the prefrontal cortex protects Aβ1–42-induced cognitive and memory impairment in the novel object recognition, step-down passive avoidance, and eight-arm maze tests." (PMID 34539384, 2021).
nasopharyngeal carcinoma (2 papers, 2014 to 2019). A carcinoma arising from the nasopharyngeal epithelium. "Previous studies have reported that knockdown of PDE4D resulted in EGFR/PI3K/AKT signaling inactivation in nasopharyngeal carcinoma cells." (PMID 31772658, 2019). "The present study first investigated the function of PDE4D in nasopharyngeal carcinoma (NPC)." (PMID 25289091, 2014).
steatosis (2 papers, 2025). Increased lipid within the cytoplasm of cells. "Still, we cannot exclude that increased hepatic PDE4D expression and impaired glucagon‐cAMP signalling contribute to hepatic steatosis in Atp8b1 mutant mice." (PMID 40851490, 2025). "Notably, PDE4D overexpression in mouse liver increased CD36 expression, suggesting that the PDE4D‐CD36 axis might contribute to the hepatic steatosis observed in Atp8b1 mutant mice." (PMID 40851490, 2025). "Interestingly, D159687 did not affect CDAHFD-induced steatosis, but this is consistent with the observation that PDE4D expression is not increased in steatosis." (PMID 41196648, 2025).
abscess (1 paper, 2018). An inflammatory process characterized by the accumulation of pus within a newly formed tissue cavity which is the result of a bacterial, fungal, or parasitic infection or the presence of a foreign body. "GO analysis with the unique differential promoters involved in Munro’s abscess formation revealed neutrophil and leukocyte chemotaxis as the highest enriched biological processes which include genes like HRH1, PDE4D, CCL25, AIF1, ADAM10, FFAR2, IL1B and TREM1." (PMID 30092825, 2018).
airway hyperresponsiveness (1 paper, 2014). "So, our study first suggested that PDE4D upregulation was induced by iBp and was involved in airway hyperresponsiveness." (PMID 25120928, 2014). "This increased airway hyperresponsiveness is causally related to decreased lung cAMP levels, increased PDE4 enzymatic activity, and PDE4D isoform-specific mRNA expression in the lung." (PMID 25120928, 2014). "In summary, our results showed that inactivated B. pertussis specifically induces the PDE4D expression and airway hyperresponsiveness, rather than inducing inflammation in the lung and upregulating the total PDE activity." (PMID 25120928, 2014).
Airway obstruction (1 paper, 2014). Obstruction of conducting airways of the lung. "Recruitment of eosinophils in airway inflammation is no different in mice deficient in PDE4D than in wild type control mice, however in the PDE4 knock out mice, methacholine induced airway obstruction was eliminated." (PMID 25351474, 2014).
allergic rhinitis (1 paper, 2021). Inflammation of the nasal mucous membranes caused by an IgE-mediated response to external allergens. "The potential role of PDE4 inhibitors in allergic rhinitis is related to the differential PDE4D gene expression in patients with allergic rhinitis and nasal polyposis." (PMID 34434103, 2021).
anorexia nervosa (1 paper, 2023). A disorder most often seen in adolescent females characterized by a refusal to maintain a minimally normal body weight, an intense fear of gaining weight, a disturbance in body image, and, in postmenarcheal females, the development of amenorrhea. "Furthermore, psychiatric disorders also had some causal effects on PDEs [obsessive–compulsive disorder on increased PDE6D and decreased PDE2A and PDE4D; anorexia nervosa on decreased PDE9A]." (PMID 37605207, 2023).
arteriosclerosis (1 paper, 2023). A vascular disorder characterized by thickening and hardening of the walls of the arteries. "In the pathogenesis of IS, PDE4D can inhibit the proliferation and migration of vascular smooth muscle cells to cause arteriosclerosis." (PMID 37508970, 2023).
Arthritis (1 paper, 2025). Inflammation of a joint. "In the present study, we demonstrate that the reduced cAMP levels in FLSs are caused by the elevated PDE4D and that PDE4D is involved in the abnormal proliferation of FLSs, leading to the worsening of arthritis." (PMID 39990667, 2025). "Collectively, these results demonstrate that Grk2 deficiency reduces PDE4D expression and effectively ameliorates the severity and progression of experimental arthritis." (PMID 39990667, 2025). "Both genetic deficiency and pharmacological inhibition of GRK2 decreased PDE4D expression, ameliorating arthritis severity in animal models." (PMID 39990667, 2025). "Genetic deficiency of Pde4d reduced arthritis severity in CIA mice." (PMID 39990667, 2025). "Both genetic deficiency and pharmacological inhibition of GRK2 have remarkably reduced PDE4D expression, consequently ameliorating the severity and progression of arthritis in animal models." (PMID 39990667, 2025). "In future investigations, we aim to establish mice with specific knockout of Pde4d or Grk2 in FLSs and induce experimental arthritis models." (PMID 39990667, 2025). "Deleting Pde4d significantly reduced disease incidence, severity, swollen joint count, and arthritis index in Pde4d-/- CIA mice compared with Pde4d+/+ CIA littermates." (PMID 39990667, 2025). "In this study, we demonstrated a significantly upregulation of PDE4D in FLSs from both RA patients and experimental arthritis models, which contributes to the hyperproliferation of FLSs." (PMID 39990667, 2025). "Strikingly, global Pde4d deletion significantly alleviated the severity and progression of arthritis induced by collagen." (PMID 39990667, 2025). "Crucially, utilizing Grk2-deficient mice, we showed that endogenous Grk2 knockdown significantly decreased PDE4D expression, alleviating arthritis symptoms in the CAIA model." (PMID 39990667, 2025). "In this study, we confirmed GRK2 overexpression in the synovium of RA patients and arthritis animal models, demonstrating its co-localization with PDE4D in RA synovium and its regulation of PDE4D expression in FLSs." (PMID 39990667, 2025). "Our study reveals abundant PDE4D expression in both synovial tissues from experimental arthritis animals and RA patients." (PMID 39990667, 2025). "Firstly, it would be more convincing to induce an experimental arthritis model in FLSs-specific Pde4d or Grk2 deletion mice." (PMID 39990667, 2025). "Global deletion of Pde4d reduces the arthritis incidence and severity in CIA mice." (PMID 39990667, 2025). "Furthermore, pharmacological inhibition of GRK2 by CP-25 substantially suppressed PDE4D expression and impeded arthritis development in the CIA model." (PMID 39990667, 2025). "Global deletion of Pde4d reduced disease incidence and alleviated arthritis in CIA mice." (PMID 39990667, 2025). "In this experiment, Pde4d-/- CIA mice demonstrated reduced disease incidence and severity, exemplified by a diminished arthritis index." (PMID 39990667, 2025). "Abundant expression of both PDE4D and GRK2 was observed in synovial tissues from both experimental arthritis animals and RA patients, with synchronized expression noted in RA patients." (PMID 39990667, 2025). "Moreover, histopathological analysis (HE and SO/FG staining) revealed milder arthritis symptoms in Pde4d-/- CIA mice, with reduced hyperplastic synovium, inflammatory cells, vascularization, cartilage destruction, and joint space narrowing compared with Pde4d+/+ CIA mice." (PMID 39990667, 2025). "Pde4d knockout significantly ameliorated paw swelling and diminished power Doppler signals (reflecting vascularization and blood flow in the synovium) in CIA mice, while normal Pde4d+/+ and Pde4d-/- mice (without immunization) showed no arthritis disorders." (PMID 39990667, 2025).
bladder tumors (1 paper, 2018). "Statistically, the PDE4D expression was found to be significantly lower in the bladder tumor tissues than that in adjacent normal bladder tissues (P = 0.009), and the low PDE4D expression was positively correlated to the poor prognosis." (PMID 30482227, 2018). "In this study, lower expression of PDE4D and higher TPL2 phosphorylation were found in the bladder tumor tissues than that in the adjacent normal tissues and correlated with poor prognosis." (PMID 30482227, 2018). "Unlike PDE4D expression, the level of TPL2 phosphorylation was found to be significantly higher in the bladder tumor tissues than that in the adjacent bladder normal tissues (P = 0.003), and the high level of pTPL2 was positively correlated to poor prognosis." (PMID 30482227, 2018).
brain tumor (1 paper, 2014). "Our findings indicate that induction of growth arrest and neural differentiation via cAMP/CREB signaling pathway by CG500354 treatment suggests the novel targeting of PDE4D in the development of new drugs for brain tumor therapy." (PMID 24989033, 2014).
celiac disease (1 paper, 2023). An autoimmune genetic disorder with an unknown pattern of inheritance that primarily affects the digestive tract. "Plasma PDE4D exhibited a positive correlation with increased risks of CRC and digestive disorders, specifically Celiac disease and non-celiac intestinal malabsorption." (PMID 38049731, 2023).
Cirrhosis (1 paper, 2025). A chronic disorder of the liver in which liver tissue becomes scarred and is partially replaced by regenerative nodules and fibrotic tissue resulting in loss of liver function. "Supporting our hypothesis that PDE4D promotes inflammatory cell infiltration, CCL2 levels in the livers of patients with cirrhosis were significantly increased compared with healthy individuals and correlated with PDE4D levels." (PMID 41196648, 2025).
developmental delay (1 paper, 2025). "A PDE4D variant was identified using a CBD panel in a cousin of the proband, who exhibited both short stature and developmental delay." (PMID 41464128, 2025).
diabetes (1 paper, 2025). "β-blocker carvedilol attenuated insulin-induced PDE4D induction and restored cAMP level to prevent diabetes-associated cardiac dysfunction." (PMID 40015131, 2025).
dilated cardiomyopathy (1 paper, 2025). Cardiomyopathy which is characterized by dilation and contractile dysfunction of the left and right ventricles. "In cardiomyocytes of PDE4d−/− mice, the absence of PDE4D enhances nuclear PKA responses to βAR stimulation, contributing to late-onset dilated cardiomyopathy." (PMID 40136709, 2025).
endotoxemia (1 paper, 2020). "We demonstrated that PDE4B but not PDE4D blockage is essential to obtain a therapeutic effect in animal models of immune-mediated hepatitis, autoimmune rheumatoid arthritis, and endotoxemia." (PMID 31899535, 2020).
familial dilated cardiomyopathy (1 paper, 2025). A a genetic form of heart disease that occurs when heart (cardiac) muscle becomes thin and weakened in at least one chamber of the heart, causing the open area of the chamber to become enlarged (dilated). "In patients with different HF types, cardiac PDE4D expression was increased in hypertrophic cardiomyopathy and peripartum cardiomyopathy but decreased in familial dilated cardiomyopathy compared to non-diseased donors (GEO Accession GSE2656)." (PMID 40015131, 2025).
fibrosis (1 paper, 2025). the formation of excess fibrous connective tissue in an organ or tissue in a reparative or reactive process. "The Pde4d, Col1a1, and Acta2 were also upregulated in carbon tetrachloride–induced (CCl4-induced) fibrosis." (PMID 41196648, 2025).
head and neck cancer (1 paper, 2014). A primary or metastatic malignant neoplasm affecting the head and neck. "Phosphodiesterase 4D (PDE4D) is a subtype of metallohydrolases, and it has been reported that PDE4D functions as a proliferation promoting factor in certain types of cancer, including head and neck cancer." (PMID 25289091, 2014).
hypopharyngeal cancers (1 paper, 2022). Carcinoma, predominantly squamous cell, arising from the epithelial cells of the hypopharynx. "Herein, we newly demonstrated that 4 genes (and the proteins) as the most powerful exploratory markers for response prediction to TXT, CDDP, and 5-FU- namely, AGR2, and PDE4D for TXT; NINJ2 and possibly RAB15 for CDDP, and CDC25B for 5-FU- in hypopharyngeal cancers." (PMID 35841085, 2022).
keloid (1 paper, 2024). An irregularly shaped, elevated mark on the skin caused by deposits of excessive amounts of collagen during wound healing. "In our study, we observed that PDE4B was the most abundantly expressed isoform in the epidermis of hypertrophic scars and keloids, followed by PDE4D." (PMID 39223490, 2024). "The analysis of PDE4 subtypes showed PDE4B the most overexpressed in keratinocytes from hypertrophic scars and keloids followed by PDE4D expression and in a lesser extent by PDE4A and PDE4C." (PMID 39223490, 2024).
kidney damage (1 paper, 2023). "Thus, these and our previous findings indicated that PDE4D in the liver plays a key role in NAFLD and sequelae of kidney damage." (PMID 37072403, 2023).
language disorder (1 paper, 2022). A category of disorders characterized by an impairment in the development of an individual's language capabilities, which is in contrast to his/her non-verbal intellect. "The genes PDE4D, FOXP2, and EML6 code for a cAMP phosphodiesterase, a transcription factor implicated in a speech and language disorder, and a microtubule associated protein, respectively." (PMID 36192459, 2022).
liver disease (1 paper, 2025). "Here, we report that PDE4D expression is specifically elevated during the hepatic fibrosis stage of liver disease progression." (PMID 41196648, 2025). "Specificity of PDE4D upregulation in fibrotic liver disease stages." (PMID 41196648, 2025). "Thus, the upregulation of PDE4D expression is specific to the fibrotic stage in the liver disease progression and may serve as a potential molecular diagnostic marker." (PMID 41196648, 2025).
liver fibrosis (1 paper, 2025). "We performed BDL in both WT and PDE4D-knockout mice to determine the role of PDE4D in liver fibrosis." (PMID 41196648, 2025). "Our study advances the search for liver fibrosis treatment by identifying a target as the long isoforms of PDE4D." (PMID 41196648, 2025). "Selective PDE4D inhibition ameliorates liver fibrosis through regulating profibrogenic and inflammatory signaling networks." (PMID 41196648, 2025). "In a mouse model of liver fibrosis, genetic ablation of PDE4D or pharmacological inhibition using D159687, a selective allosteric inhibitor targeting the long isoforms of PDE4D, suppresses the expression of inflammatory and profibrogenic genes." (PMID 41196648, 2025). "Taking advantage of these converging properties, we used D159687 to investigate the role of the long isoforms of PDE4D in liver fibrosis." (PMID 41196648, 2025). "Together, these findings suggest that upregulation of long isoforms of PDE4D by TGFb contributes to liver fibrosis by enhancing the expression of profibrotic genes in HSCs." (PMID 41196648, 2025). "Selective inhibition of long PDE4D isoforms mitigates liver fibrosis progression." (PMID 41196648, 2025). "Since PDE4D expression is upregulated during the hepatic fibrosis stage and throughout the transdifferentiation of HSCs into myofibroblast-like cells, we asked whether TGFb regulates PDE4D expression." (PMID 41196648, 2025). "Therefore, targeting the long isoforms of PDE4D may be effective for treating other fibrotic diseases as well as liver fibrosis." (PMID 41196648, 2025).
lung diseases (1 paper, 2024). "Since PDE4D/AK7 has been previously linked to cAMP/ATP metabolism in lung diseases and now to miR-370-5p in ASMCs, we thus evaluated the effect of high stretch on the cAMP/ATP level inside ASMCs." (PMID 38247802, 2024). "Since PDE4D/AK7 have been previously linked to cAMP/ATP metabolism in lung diseases and now to miR-370-5p in ASMCs, we thus evaluated the effect of high stretch on the cAMP/ATP level inside ASMCs." (PMID 38247802, 2024).
lymph node metastasis (1 paper, 2019). "High level of PDE4D was significantly associated with clinical stage (P = 0.004), T classification (P = 0.003), lymph node metastasis (P = 0.022) and liver metastasis (P = 0.038)." (PMID 31772658, 2019). "For the first time, we demonstrated that overexpression of PDE4D was correlated with clinical stage (pTNM), lymph node metastases and liver metastases in PDAC." (PMID 31772658, 2019).
multiple sclerosis (1 paper, 2024). A progressive autoimmune disorder affecting the central nervous system resulting in demyelination. "In addition, PDE4D inhibition promoted in vivo re-myelination in a model of multiple sclerosis (MS), without triggering emesis-like side effects in rodents." (PMID 39125619, 2024).